RNF145 (ring finger protein 145)
Description:
E3 ubiquitin ligase that catalyzes the direct transfer of ubiquitin from E2 ubiquitin-conjugating enzyme to a specific substrate. In response to bacterial infection, negatively regulates the phagocyte oxidative burst by controlling the turnover of the NADPH oxidase complex subunits. Promotes monoubiquitination of CYBA and 'Lys-48'-linked polyubiquitination and degradation of CYBB NADPH oxidase catalytic subunits, both essential for the generation of antimicrobial reactive oxygen species. Involved in the maintenance of cholesterol homeostasis. In response to high sterol concentrations ubiquitinates HMGCR, a rate-limiting enzyme in cholesterol biosynthesis, and targets it for degradation. The interaction with INSIG1 is required for this function. In addition, triggers ubiquitination of SCAP, likely inhibiting its transport to the Golgi apparatus and the subsequent processing/maturation of SREBPF2, ultimately down-regulating cholesterol biosynthesis.
Synonyms: FLJ31951
Tractability: Antibody: UniProt predicts a signal peptide or a membrane-spanning region; the Human Protein Atlas places it where antibodies can reach. PROTAC: ubiquitination databases record sites on it.
Gene: Protein-coding gene on chromosome 5 (159,157,409 to 159,210,053, reverse strand). Ensembl gene ENSG00000145860.
Subcellular location: Endoplasmic reticulum membrane
Subcellular location (Human Protein Atlas): Cytosol; Nucleoplasm; Plasma membrane
Gene Ontology:
Molecular function: ubiquitin protein ligase activity; zinc ion binding
Biological process: proteasome-mediated ubiquitin-dependent protein catabolic process
Cellular component: endoplasmic reticulum membrane
Genetic constraint (gnomAD): Loss-of-function variants: 7 observed, 36.83 expected, observed/expected ratio (o/e) 0.19, 90% interval 0.11 to 0.36. The upper end of that interval is the gene's LOEUF score, 0.36, which puts it in group 1 of 6, group 1 being the genes least tolerant of losing a copy. Missense variants: 364 observed, 679.32 expected, observed/expected ratio (o/e) 0.54, 90% interval 0.49 to 0.58. Synonymous variants: 224 observed, 243.4 expected, observed/expected ratio (o/e) 0.92, 90% interval 0.82 to 1.03.
Homologues: Orthologues: chimpanzee RNF145 (99% identical), macaque RNF145 (99% identical), dog RNF145 (97% identical), pig RNF145 (96% identical), rabbit RNF145 (95% identical), rat Rnf145 (95% identical), mouse Rnf145 (94% identical), guinea pig RNF145 (93% identical), tropical clawed frog rnf145 (86% identical), zebrafish rnf145b (80% identical), zebrafish rnf145a (79% identical), Caenorhabditis elegans sel-11 (13% identical), and 1 more. Paralogues in human: RNF139 (24% identical), SYVN1 (15% identical), AMFR (15% identical), DZIP3 (14% identical).
Diseases named in the same sentence as RNF145 in open-access papers:
RNF145 is named in the same sentence as 11 diseases in open-access papers, as found by Europe PMC text mining. Sharing a sentence is not in itself a finding about the gene and the disease. The quoted sentences say what the papers report.
Obesity (2 papers, 2019 to 2021). Accumulation of substantial excess body fat. "In this example, 16 DMSs in genes, such as CPT1A, ABCG1, SLC7A11, RNF145, and SREBF1 were reported to be associated with obesity-related phenotypes." (PMID 35047011, 2021).
dyslipidemia (1 paper, 2021). "Thus, we speculate that there may be a correlation between the RNF145 gene and dyslipidemia." (PMID 33727652, 2021).
Hypercholesterolemia (1 paper, 2021). An increased concentration of cholesterol in the blood. "Studies have shown that RNF145 can inhibit endogenous cholesterol synthesis and effectively treat hypercholesterolemia." (PMID 33727652, 2021). "The E3 ubiquitin ligase which is encoded by the ring finger protein 145 (RNF145) gene is very important in the mediation of cholesterol synthesis and effectively treats hypercholesterolemia." (PMID 33727652, 2021). "Our research suggests that the RNF145 gene may be a target to lower cholesterol levels and treat hypercholesterolemia." (PMID 33727652, 2021).
cancer (2 papers, 2022 to 2023). A tumor composed of atypical neoplastic, often pleomorphic cells that invade other tissues. "Based on these findings, splicing disruption of RNF145 warrants further investigation as a potential driver mechanism underlying MSI-H cancers." (PMID 36949070, 2023). "Through ENCORI database with the specific condition (strict stringency; 10 cancer types), three possible mRNAs were observed to be shared by miR-362-5p and miR-500b-5p, which were RNF145, SAMD4A (sterile alpha motif domain containing 4A) and ATP2B4 (ATPase plasma membrane Ca2+ transporting 4)." (PMID 35365168, 2022).
tumor (2 papers, 2022 to 2025). "Altogether, RNF145 exerts a tumor-facilitating function in OSCC." (PMID 35365168, 2022). "In conclusion, circZDBF2 accelerates in vivo OSCC tumor growth by regulating RNF145, p65 and IL-8." (PMID 35365168, 2022). "E3 ligases such as RNF145, gp78, and HRD1 promote HMGCR degradation, while ubiquitin-specific protease 20 (USP20) stabilizes HMGCR, enhancing cholesterol synthesis and driving tumor growth." (PMID 40370434, 2025).
cardiovascular diseases (1 paper, 2021). "However, at present, there are few studies on the relationship between RNF145 and cardiovascular diseases." (PMID 33727652, 2021).
RNF145 also shares sentences with these, for which no sentence is quoted: breast carcinoma (1 paper); hepatocellular carcinoma (1); oral squamous cell carcinoma (1); psoriatic arthritis (1); renal carcinoma (1).